FMOD (fibromodulin)
Description:
Affects the rate of fibrils formation. May have a primary role in collagen fibrillogenesis (By similarity).
Synonyms: FM; SLRR2E
Tractability: Antibody: its Gene Ontology location is reachable by antibodies, with high confidence; UniProt places it where antibodies can reach, with medium confidence; UniProt predicts a signal peptide or a membrane-spanning region.
Gene: Protein-coding gene on chromosome 1 (203,340,623 to 203,351,758, reverse strand). Ensembl gene ENSG00000122176.
Subcellular location: Secreted, extracellular space, extracellular matrix
Pathways (Reactome):
Disease: Defective B4GALT1 causes B4GALT1-CDG (CDG-2d); Defective CHST6 causes MCDC1; Defective ST3GAL3 causes MCT12 and EIEE15
Metabolism: Keratan sulfate biosynthesis; Keratan sulfate degradation
Extracellular matrix organization: ECM proteoglycans
Gene Ontology:
Molecular function: extracellular matrix structural constituent conferring compression resistance
Biological process: transforming growth factor beta receptor complex assembly; collagen fibril organization
Cellular component: extracellular matrix; extracellular region; gel phase of interstitial matrix; Golgi lumen; lysosomal lumen
Genetic constraint (gnomAD): Loss-of-function variants: 15 observed, 28.69 expected, observed/expected ratio (o/e) 0.52, 90% interval 0.35 to 0.81. The upper end of that interval is the gene's LOEUF score, 0.81, which puts it in group 3 of 6, group 1 being the genes least tolerant of losing a copy. Missense variants: 460 observed, 505.96 expected, observed/expected ratio (o/e) 0.91, 90% interval 0.84 to 0.98. Synonymous variants: 210 observed, 225.13 expected, observed/expected ratio (o/e) 0.93, 90% interval 0.83 to 1.05.
Homologues: Orthologues: chimpanzee FMOD (100% identical), macaque FMOD (99% identical), pig FMOD (95% identical), dog FMOD (94% identical), guinea pig FMOD (93% identical), mouse Fmod (93% identical), rat Fmod (93% identical), rabbit FMOD (81% identical), tropical clawed frog fmod (59% identical), zebrafish fmodb (50% identical), zebrafish fmoda (50% identical). Paralogues in human: LUM (40% identical), PRELP (38% identical), KERA (35% identical), OMD (34% identical), ECM2 (28% identical), LINGO3 (21% identical), LINGO4 (20% identical), EPYC (17% identical), OGN (17% identical), OMG (17% identical).
Diseases named in the same sentence as FMOD in open-access papers:
FMOD is named in the same sentence as 79 diseases in open-access papers, as found by Europe PMC text mining. Sharing a sentence is not in itself a finding about the gene and the disease. The quoted sentences say what the papers report.
glioma (10 papers, 2018 to 2024). A benign or malignant brain and spinal cord tumor that arises from glial cells (astrocytes, oligodendrocytes, ependymal cells). "In line with our previous findings indicating that TGF-β signaling controls FMOD expression in glioma, we next explored the possible role of this pathway in FMOD overexpression in DGCs." (PMID 35642785, 2022). "Differentiated glioma cell (DGC)-secreted fibromodulin (FMOD) promotes angiogenesis of host-derived and tumor-derived endothelial cells." (PMID 35642785, 2022). "This was consistent with a study in glioma, showing that FMOD regulates cell migration via activation of the integrin-FAK-dependent pathway." (PMID 35737114, 2022). "Collectively, these findings indicate that DGC-secreted FMOD is essential for the growth of both human and mouse glioma." (PMID 35642785, 2022). "FMOD promotes glioma cell migration through actin cytoskeleton remodeling mediated by an integrin-FAK-Src-Rho-ROCK signaling pathway but does not affect colony-forming ability, growth on soft agar, chemosensitivity, and glioma cell proliferation." (PMID 35642785, 2022). "Conditional silencing of fibromodulin (FMOD) in differentiated glioma cells (DGCs) formed de novo by glioma stem-like cell (GSC)-initiated tumors inhibits tumor growth." (PMID 35642785, 2022). "From these results, we conclude that angiogenesis induced by DGC-secreted FMOD is essential for glioma tumor growth." (PMID 35642785, 2022). "The study also highlights the potential of GSC and DGC CM analysis to uncover novel targets in cancer therapy and the critical influence of DGC-secreted FMOD in glioma tumor growth." (PMID 35642785, 2022). "Differentiated glioma cell (DGC)-secreted fibromodulin (FMOD) is essential for tumor growth initiated by glioma stem-like cells (GSCs) in vivo in a co-implantation experiment." (PMID 35642785, 2022). "We used LN229 and U251 glioma cells, which express low and high levels of FMOD, respectively, for overexpression and silencing studies." (PMID 35642785, 2022). "Quantitative proteomics shows a higher abundance of fibromodulin under the control of TGF-β signaling in the differentiated glioma cell (DGC) secretome." (PMID 35642785, 2022). "Our previous study showed that FMOD acts on glioma cells via the integrin-FAK-Src-Rho axis to promote migration." (PMID 35642785, 2022). "Reduced angiogenesis is characteristic of tumors initiated by fibromodulin (FMOD)-silenced glioma cells." (PMID 35642785, 2022). "Mondal and colleagues demonstrated that tumor secreted FMOD activates integrin-FAK-Src-Rho GTPase-dependent signaling to induce the migration of glioma cells." (PMID 31198406, 2019). "It has been recently observed that FMOD silencing significantly inhibits the TGF-β1-mediated migration of glioma cells." (PMID 31198406, 2019). "The loss of FMOD expression hampers the migratory function of glioma cells but has no impact on glioma cell proliferation." (PMID 35642785, 2022). "Growth of human glioma stem-like cell (GSC)-initiated tumors requires secreted fibromodulin (FMOD)." (PMID 35642785, 2022). "In addition, we previously found a significant enrichment of the term ‘angiogenesis’ among differentially regulated genes in FMOD-silenced U251 glioma cells." (PMID 35642785, 2022). "Both FMOD promoter methylation and transcript levels predict prognosis in gliomas." (PMID 34805164, 2021). "Fibromodulin (FMOD) was upregulated in glioma and could promote glioma cell migration by inducing the formation of filamentous actin stress fibers." (PMID 34805164, 2021). "In contrast, a recent more comprehensive study on FMOD in glioblastoma (GBM) indicated that FMOD is required for glioma cell migration, and that FMOD induces glioma cell migration induced by FMOD occurred via the activation of the FAK-Src-Rho-ROCK signaling pathway." (PMID 31824307, 2019).
glioma (continued). "In addition, using siRNA and inhibitor-based small molecules revealed that integrin-FAK-Src-Rho-ROCK signaling pathway is very important signaling pathway which is related to FMOD-induced glioma cell migration." (PMID 31198406, 2019). "Yet little was known about the molecular and cellular mechanisms by which FMOD expression is regulated, and only one study has been reported which suggested that FMOD transcription in glioma cells is positively regulated by the TGF-β1/SMAD2 pathway by an epigenetic mechanism." (PMID 31824307, 2019). "To further verify the correlations of PD-L1 with FMOD, MXRA5 and RAB36, we established a mouse model using CT2A and GL261 mouse glioma cells." (PMID 39513108, 2024). "FMOD directly interacts with TGF-β by regulating the action of local TGF-β within ECM, and works as a crucial regulator of glioma cell migration in the downstream of TGF-β1 pathway." (PMID 36986805, 2023). "This is consistent with our previous findings indicating that FMOD activates integrin signaling via type I collagen to engage the FAK-Src-Rho-ROCK pathway and promote the migration of glioma cells." (PMID 35642785, 2022). "To determine the relevance of our findings to the human pathology, we investigated the importance of DGC-secreted FMOD in the growth of tumors initiated by MGG8 and U251 cells using a xenograft mouse glioma model." (PMID 35642785, 2022). "DBT-Luc GSC/miRFMOD, another murine glioma GSC cell line, produced similar results: FMOD silencing after doxycycline administration resulted in reduced tumor growth, increased mice survival, and decreased FMOD expression." (PMID 35642785, 2022). "Fibromodulin (FMOD), as a GBM-upregulated gene, promotes glioma cell migration through its ability to generate the formation of filamentous actin stress fibers." (PMID 31508371, 2019). "Collectively, these findings demonstrate that DGC-secreted FMOD promotes glioma tumor angiogenesis and growth through paracrine signaling in endothelial cells and identifies a DGC-produced protein as a potential therapeutic target in glioma." (PMID 35642785, 2022). "Proteomic analysis showed a higher abundance of the extracellular matrix small leucine-rich proteoglycan fibromodulin (FMOD) in the conditioned medium of differentiated glioma cells (DGCs), the equivalent of glioma non-CSCs, compared to that of glioma stem-like cells (GSCs)." (PMID 35642785, 2022). "Toward exploring the possible role of DGC-secreted FMOD in glioma tumor growth, we first investigated the role of FMOD in GSC and DGC growth and interconversion between both cell populations in vitro using two human (MGG8 and U251) and two murine (AGR53 and DBT-Luc) glioma cell lines." (PMID 35642785, 2022). "Therefore, CLEC5A, FMOD, FKBP9, and LGALS8 could be considered crucial prognostic factors in the OS of glioma patients." (PMID 31508371, 2019). "It has been showed that FMOD without C-terminus LRR11 domain (ΔFMOD) is not able to bind collagen type I and could not also induce integrin and glioma cell migration." (PMID 31198406, 2019). "We found that the absence of FMOD neither affected GSC growth and differentiation to DGC nor DGC growth and reprogramming to form GSCs (more details in Appendix 1), consistent with our previous findings showing that FMOD does not affect glioma cell proliferation in vitro." (PMID 35642785, 2022).
glioblastoma (9 papers, 2018 to 2025). The most malignant astrocytic tumor (WHO grade IV). "The FMOD gene is a novel biomarker for prostate cancer, but it was found also upregulated in glioblastoma." (PMID 29844869, 2018). "In glioblastoma cells, upregulated fibromodulin binds to collagen type I and promotes the activation of integrin-FAK-Src-Rho-ROCK signaling cascade causing tumor cell migration, while in lung cancer, fibromodulin promotes angiogenesis by increasing the expression of angiogenic factors." (PMID 36342580, 2023). "In other cancer categories, multiple studies have reported an association of upregulation of FMOD with poor patient survival in TCGA glioblastoma patients, and its product has been suggested to have an immunosuppressive role, whereas the silencing of FMOD leads to apoptosis in CCLE." (PMID 33676569, 2021). "Moreover, it has been demonstrated that FMOD gene is up-regulated in highly malignant glioblastoma compared with relatively benign pilocytic astrocytoma." (PMID 31198406, 2019).
osteoarthritis (9 papers, 2011 to 2023). A noninflammatory degenerative joint disease occurring chiefly in older persons, characterized by degeneration of the articular cartilage, hypertrophy of bone at the margins and changes in the synovial membrane. "Since FMOD whole protein is now easy to produce, further in-depth investigations are warranted to reveal the underlying mechanism of action of FMOD as a new generation disease-modifying osteoarthritis drug candidate." (PMID 31920661, 2019). "FMOD-null mice exhibited a higher incidence of osteoarthritis in knee joints, which occurred at 36 weeks in the articular cartilage, subchondral bone, ligaments, and menisci, while the ECM and type II fibrils were not altered in the articular cartilage." (PMID 37483637, 2023). "In particular, the gene FMOD (fibromodulin) a collagen-binding molecule expressed in connective tissues is particularly interesting given its role in pathobiology in osteoarthritis of the temporomandibular joint." (PMID 33192958, 2020). "A number of rodent models involving FMOD gene knockouts have shown accelerated osteoarthritis in the temporomandibular joint, as compared to wildtype animals." (PMID 33192958, 2020). "Opticin null mice showed protection against osteoarthritis and it was found that these mice had increased levels of lumican and epiphycan, and decreased levels of fibromodulin." (PMID 32764753, 2020). "Recent studies have identified that FMOD plays a vital role in the progression of osteoarthritis." (PMID 37483637, 2023). "Moreover, the fragmentation of FMOD may affect the ability of its binding with collagen and active complement which are both involved in the progression of osteoarthritis." (PMID 37483637, 2023). "According to a biglycan and fibromodulin double-deficient mouse model, osteoarthritis-related cartilage and bony defects in the TMJ were not identified until the age of 9 months although some histological changes in the condylar cartilage were found amongst 3-month-olds." (PMID 22003394, 2011). "Notably, the collagen fibrils in the articular cartilage of the FMOD-deficient mice were also not different from those observed in the WT cartilage, which suggests that the osteoarthritis was not caused by collagen defects in the articular cartilage of FMOD null mice." (PMID 37483637, 2023). "By the way, the degradation of articular cartilage in osteoarthritis is thought to be the results of ADAMTS5 and likely also of ADAMTS4 activity, two enzymes thought to be involved in degradation of certain SLRPs, e.g., of fibromodulin as well." (PMID 33028365, 2020). "Inhibitors of WNT (DKK3 and FRZB), and antagonists of BMP/TGFβ (CD109, CHRDL2, DCN FMOD, INHBA and THBS1) signalling were decreased or absent in the aged inner region, consistent with the reported upregulation of these pathways in IDD and its closely related condition osteoarthritis." (PMID 33382035, 2020).
heart failure (8 papers, 2018 to 2025). Inability of the heart to pump blood at an adequate rate to meet tissue metabolic requirements. "In patients and animals with heart failure, FMOD expression is enhanced in myocardial biopsies, contributing to inflammation and AF." (PMID 37904680, 2023). "This is the case of FMOD, whose expression is upregulated in clinical and experimental heart failure or MFAP4, a protein whose abrogation in mice worsens cardiac function upon chronic pressure overload." (PMID 37565451, 2023). "In conclusion, despite a robust fibromodulin upregulation in clinical and experimental heart failure, FMOD-KO mice showed a relatively mild hypertrophic phenotype." (PMID 30052659, 2018). "It is a type of fibromodulin that is upregulated in clinical and experimental heart failure." (PMID 38077583, 2023). "FMOD has been identified as upregulated DEGs in heart failure." (PMID 38077583, 2023). "Fibromodulin was 3-10-fold upregulated in hearts of heart failure patients and mice." (PMID 30052659, 2018). "Upregulated genes in Vehicle include NPPB, COL1A1, FMOD, LOX and MMP9, among others, some of which are related with pro-fibrotic processes and heart failure." (PMID 37342444, 2023). "FMOD and LUM, for example, are increased in heart failure as a response to inflammation and play a role in cardiac remodeling." (PMID 32670412, 2020). "Our study proposes that circulating levels of FMOD and FBLN5 may serve as new biomarkers of RVD in patients with heart failure with reduced ejection fraction." (PMID 39823288, 2025). "In conclusion, previous studies have suggested that FMOD may play an important role in the inflammatory response and ECM remodeling during heart failure." (PMID 37483637, 2023). "We investigated fibromodulin levels in myocardial biopsies from heart failure patients and mice, subjected fibromodulin knock-out (FMOD-KO) mice to pressure overload by aortic banding, and overexpressed fibromodulin in cultured cardiomyocytes and cardiac fibroblasts using adenovirus." (PMID 30052659, 2018).
leiomyoma (6 papers, 2007 to 2025). A well-circumscribed benign smooth muscle neoplasm characterized by the presence of spindle cells with cigar-shaped nuclei, interlacing fascicles, and a whorled pattern. "FMOD has been recognized as a novel tumor-associated antigen in lymphoma, leiomyoma, and leukemia, and FMOD has been detected in various clinical malignancies, such as breast, prostate, and lung carcinomas." (PMID 34283070, 2021). "Other studies revealed FMOD as a novel tumor-associated antigen in leukemia, lymphoma, and leiomyoma." (PMID 24603701, 2014). "FMOD has been recognized as a novel tumor-associated antigen in lymphoma, leiomyoma, and leukemia." (PMID 31198406, 2019). "For example, treatment with gonadotropin-releasing hormone analogs reduced fibromodulin expression in fibroid tissues to physiological levels, while all-trans retinoic acid suppressed leiomyoma cell proliferation by downregulating versican." (PMID 41228294, 2025). "Besides these roles, FMOD has been considered as a new tumor-related antigen in some malignancies such as lymphoma, leukemia, and leiomyoma." (PMID 31198406, 2019). "The expression of many components of ECM including collagens, decorin, versican, fibromodulin, intergrins, extracellular matrix protein 1 (ECM-1), syndecan and ESM-1 has been identified in leiomyomas as well as dermal wounds during healing, scars and keloids." (PMID 17718906, 2007).
prostate carcinoma (6 papers, 2014 to 2026). A carcinoma that arises from epithelial cells of the prostate gland. "As far as we know, this is the first study to screen part of the FMOD gene, analyzing its association with prostate cancer and benign prostatic hyperplasia." (PMID 35686032, 2022). "Bettin and Reyes (2016) showed the strong interaction between prostate cancer and FMOD, revealing that the gene is highly expressed in human PCa cells, whereas in hyperplastic cells, there is no increase expression." (PMID 35686032, 2022). "Due to its product be detected in body fluids as urine, blood, or prostatic secretions, the fibromodulin coding gene has great potential to be used as a new biomarker to diagnosis of patients with benign or malignant prostate tumors." (PMID 35686032, 2022). "Both COL2A and FMOD (a COL2A1 interacting protein) have been reported as biomarkers for prostate cancer." (PMID 28027300, 2016). "For example, an expression of collagens I, II, III, IV, fibromodulin, and proteoglycans (decorin, biglycan, lumican) in stromal cells, when grown in the presence of two metastatic prostate cancer cell lines PC3 and DU145, is significantly down-regulated." (PMID 24782989, 2014). "We also show that SKP2 overexpression in prostate cancer PC3 cells increases the protein levels of TWIST1 and the expression of EMT related genes, including FMOD, THY1, NFIL3 and IRF2, leading to a marked increase in migration and invasion." (PMID 41542047, 2026).